KDM8 (lysine demethylase 8)
Description:
Bifunctional enzyme that acts both as an endopeptidase and 2-oxoglutarate-dependent monooxygenase. Endopeptidase that cleaves histones N-terminal tails at the carboxyl side of methylated arginine or lysine residues, to generate 'tailless nucleosomes', which may trigger transcription elongation. Preferentially recognizes and cleaves monomethylated and dimethylated arginine residues of histones H2, H3 and H4. After initial cleavage, continues to digest histones tails via its aminopeptidase activity. Upon DNA damage, cleaves the N-terminal tail of histone H3 at monomethylated lysine residues, preferably at monomethylated 'Lys-9' (H3K9me1). The histone variant H3F3A is the major target for cleavage. Additionally, acts as a Fe(2+) and 2-oxoglutarate-dependent monooxygenase, catalyzing (R)-stereospecific hydroxylation at C-3 of 'Arg-137' of RPS6 and 'Arg-141' of RCCD1, but the biological significance of this activity remains to be established. Regulates mitosis through different mechanisms: Plays a role in transcriptional repression of satellite repeats, possibly by regulating H3K36 methylation levels in centromeric regions together with RCCD1. Possibly together with RCCD1, is involved in proper mitotic spindle organization and chromosome segregation. Negatively regulates cell cycle repressor CDKN1A/p21, which controls G1/S phase transition. Required for G2/M phase cell cycle progression. Regulates expression of CCNA1/cyclin-A1, leading to cancer cell proliferation. Also, plays a role in regulating alpha-tubulin acetylation and cytoskeletal microtubule stability involved in epithelial to mesenchymal transition. Regulates the circadian gene expression in the liver (By similarity). Represses the transcriptional activator activity of the CLOCK-BMAL1 heterodimer in a catalytically-independent manner. Negatively regulates the protein stability and function of CRY1; required for AMPK-FBXL3-induced CRY1 degradation.
Synonyms: JMJD5; FLJ13798
Tractability: Small molecule: a structure with a bound ligand is known. PROTAC: a small molecule that binds it is known.
Target class: Enzyme; Oxidoreductase
Gene: Protein-coding gene on chromosome 16 (27,203,486 to 27,225,987, forward strand). Ensembl gene ENSG00000155666.
Subcellular location: Nucleus; Chromosome
Subcellular location (Human Protein Atlas): Nucleoplasm; Cytosol
Pathways (Reactome):
Metabolism of proteins: Protein hydroxylation
Gene Ontology:
Molecular function: aminopeptidase activity; chromatin binding; endopeptidase activity; histone H3K36 demethylase activity; peptidyl-arginine 3-dioxygenase activity; protein binding
Biological process: G2/M transition of mitotic cell cycle; negative regulation of DNA-templated transcription; positive regulation of DNA-templated transcription; protein destabilization; circadian regulation of gene expression; peptidyl-arginine hydroxylation; chromatin remodeling; regulation of gene expression
Cellular component: chromosome; nucleus; cytosol
Genetic constraint (gnomAD): Loss-of-function variants: 35 observed, 49.87 expected, observed/expected ratio (o/e) 0.7, 90% interval 0.54 to 0.93. The upper end of that interval is the gene's LOEUF score, 0.93, which puts it in group 3 of 6, group 1 being the genes least tolerant of losing a copy. Missense variants: 475 observed, 552.59 expected, observed/expected ratio (o/e) 0.86, 90% interval 0.8 to 0.93. Synonymous variants: 232 observed, 236.31 expected, observed/expected ratio (o/e) 0.98, 90% interval 0.88 to 1.1.
Homologues: Orthologues: chimpanzee KDM8 (99% identical), macaque KDM8 (95% identical), pig KDM8 (81% identical), dog KDM8 (80% identical), rat Kdm8 (78% identical), mouse Kdm8 (78% identical), guinea pig KDM8 (77% identical), tropical clawed frog kdm8 (55% identical), zebrafish kdm8 (55% identical), Caenorhabditis elegans jmjd-5 (34% identical), Drosophila melanogaster JMJD5 (34% identical). Paralogues in human: HIF1AN (20% identical), HSPBAP1 (19% identical), TYW5 (15% identical), JMJD7 (15% identical).
Diseases named in the same sentence as KDM8 in open-access papers:
KDM8 is named in the same sentence as 35 diseases in open-access papers, as found by Europe PMC text mining. Sharing a sentence is not in itself a finding about the gene and the disease. The quoted sentences say what the papers report.
breast carcinoma (14 papers, 2014 to 2025). "KDM8 overexpression has been linked to colon and breast cancer in several investigations, establishing that KDM8 deletion impairs cancer cell growth." (PMID 37218871, 2023). "Previously, we reported that in breast cancer, a novel function of KDM8 is its association with PKM2 and its ability to translocate PKM2 into nucleus to become a coactivator of HIF-1α to transcriptionally activate glycolytic genes in favor of Warburg effects." (PMID 30072740, 2019). "KDM8 promotes breast cancer cell proliferation by activating CCNA1, a regulator of the G1/S and G2/M transition." (PMID 37893043, 2023). "KDM8, a member of an evolutionarily conserved protein family with a Jumonji domain, is currently recognized as an oncogene in colon and breast cancer." (PMID 37893043, 2023). "A study showed KDM8 overexpression induced the expression of cell cycle promoter gene cyclin D1, promoting cell proliferation in a breast cancer cells model in vitro and conversely, KDM8 knockdown inhibited cell growth." (PMID 34220955, 2021). "Previously, we showed that KDM8 is involved in the regulation of cell cycle and tumor metabolism in breast cancer cells." (PMID 30072740, 2019). "Together, PKM2 exon-10 mutations lead to structure-allostery alterations and increased nuclear functions mediated by KDM8 in breast cancer cells." (PMID 30911680, 2019). "JMJD5/KDM8, a histone demethylase overexpressed in prostate and breast cancers, binds PKM2 at the dimer–dimer interface in favor of dimer formation and provides its own nuclear localization signal to recruit importin to facilitate the translocation." (PMID 40790192, 2025). "While KDM8 expression is down-regulated in liver and pancreatic tumor samples compared to adjacent non-tumor samples, it is overexpressed in breast cancer to induce EMT and invasion." (PMID 31036064, 2019).
oral squamous cell carcinoma (6 papers, 2020 to 2026). "This study aimed to investigate AITC’s impact on the KDM8/CCNA1 axis to elucidate its role in oral squamous cell carcinoma (OSCC) tumorigenesis." (PMID 37893043, 2023). "Silibinin, the active ingredient in the medicinal plant milk thistle, appears to inhibit JMJD5/KDM8 in cases of oral squamous cell carcinoma." (PMID 37218871, 2023).
lung carcinoma (5 papers, 2016 to 2025). "Similarly, another study reported that the knockdown of KDM8 promoted lung cancer cell proliferation, and xenograft tumor growth in experimental mice." (PMID 40940894, 2025). "Moreover, KDM8 reduced the proliferation and motility of lung cancer cells, and increased sensitivity to gefitinib, which pointed to its tumor suppressive function." (PMID 40940894, 2025). "KDM8 showed negative correlation with EGFR expression in lung cancer patients." (PMID 40940894, 2025).
pancreatic cancer (4 papers, 2019 to 2026). "KDM8 was a potential tumor suppressor down-regulated in liver and pancreatic cancers and an independent prognostic factor." (PMID 31036064, 2019).
oral cancers (3 papers, 2020 to 2023). "Additionally, KDM8 high expression was associated with tumor size, lymph node metastasis, and worse survival rate in oral cancer patients." (PMID 35326475, 2022). "KDM8 is highly expressed in various types of cancer such as breast, lung, stomach, prostate, colon, and oral cancers." (PMID 37893043, 2023). "As a result, this study utilizes a preclinical PDTX model and an oral cancer cell line to explore whether AITC’s anticancer effects on cell proliferation in oral cancer are modulated through KDM8 and CCNA1." (PMID 37893043, 2023). "In this regard, it was shown that silibinin inhibited KDM8 in oral cancer cells." (PMID 35326475, 2022). "KDM8 (JMJD5) was overexpressed in patients with oral cancers." (PMID 35326475, 2022). "Furthermore, knocking down KDM8 using siRNA inhibited the growth of oral cancer cells." (PMID 37893043, 2023). "To further support our observations, we performed Western blotting analysis on various oral cancer cell lines (SAS, SCC25, and HSC3) and human normal gingival fibroblast cells (HGF) to investigate KDM8 and CCNA1 expression." (PMID 37893043, 2023). "In our previous report, we demonstrated a correlation between the high expression of KDM8 and an unfavorable prognosis in OSCC, and the downregulation of JMJD5 could inhibit proliferation in the oral cancer preclinic model." (PMID 37893043, 2023). "KDM8 and CCNA1 repression by AITC markedly suppressed oral cancer’s proliferation or growth." (PMID 37893043, 2023). "Additionally, AITC downregulated KDM8 and CCNA1 expression while inducing histone H3K36me2 expression in oral cancer cells." (PMID 37893043, 2023).
prostate carcinoma (3 papers, 2019 to 2023). A carcinoma that arises from epithelial cells of the prostate gland. "KDM8 thus presents itself as an ideal therapeutic target for metabolic adaptation and castration-resistance of prostate cancer cells." (PMID 30072740, 2019). "In prostate cancer, ATAD2 can bind to the promoter of EZH2 together with KDM8 and E2F1 to promote the transcription of EZH2." (PMID 36632213, 2023). "For instance, KDM8 / JMJD5, a histone lysine demethylase/dioxygenase, directly targets ATAD2 to maintain cell survival via AR activation of EZH2 in prostate cancer." (PMID 36632213, 2023).
liver cancer (2 papers, 2019 to 2020). An epithelial or non-epithelial malignant neoplasm that arises from the liver. "Patients with high KDM8 levels had a significantly lower risk of death in pancreatic and liver cancer cohorts." (PMID 31036064, 2019). "To ascertain the biological consequences of deregulated KDM8 expression, we conducted differential expression analysis on liver cancer patients categorized into KDM8-low and -high groups." (PMID 31036064, 2019).
metastatic disease (2 papers, 2025). "In summary, Kdm8 restrains phenotypic reprogramming by limiting the loss of differentiation and expression of the EMT marker Vimentin, thereby potently suppressing metastatic disease." (PMID 40909661, 2025).
bladder cancer (1 paper, 2019). "Moreover, 5-year survival rates dropped to ~ 12% in bladder cancer patients with low expression of signature 1 genes (high-risk), which included KDM8 and PCDHA1 mutations." (PMID 31036064, 2019).
breast tumors (1 paper, 2019). "This is particularly pronounced in the presence of KDM8, an oncogenic partner highly overexpressed in breast tumors." (PMID 30911680, 2019).
dilated cardiomyopathy (1 paper, 2023). Cardiomyopathy which is characterized by dilation and contractile dysfunction of the left and right ventricles. "In humans, KDM8 was downregulated in hearts affected by dilated cardiomyopathy, and higher TBX15 expression correlated with the strongest downregulation of genes encoding mitochondrial proteins." (PMID 38665902, 2023). "Here, we show that lysine demethylase 8 (Kdm8) maintains an active mitochondrial gene network by repressing Tbx15, thus preventing dilated cardiomyopathy leading to lethal heart failure." (PMID 38665902, 2023). "NAD+ supplementation prevented dilated cardiomyopathy in Kdm8 mutant mice, and TBX15 overexpression blunted NAD+-activated cardiomyocyte respiration." (PMID 38665902, 2023). "Furthermore, KDM8 was downregulated in human hearts affected by dilated cardiomyopathy, and higher TBX15 expression defines a subgroup of affected hearts with the strongest downregulation of genes encoding mitochondrial proteins." (PMID 38665902, 2023). "Deletion of Kdm8 in mouse cardiomyocytes increased H3K36me2 with activation of Tbx15 and repression of target genes in the NAD+ pathway before dilated cardiomyopathy initiated." (PMID 38665902, 2023).
heart failure (1 paper, 2023). Inability of the heart to pump blood at an adequate rate to meet tissue metabolic requirements. "This suggests that Kdm8 coordinates the transcriptional response of the heart to NAD+ treatment in the context of heart failure." (PMID 38665902, 2023). "Altogether, our results suggest that KDM8 epigenetically controls cardiac metabolism repressing TBX15 to prevent the initiation of cardiac deterioration toward heart failure." (PMID 38665902, 2023). "Before analyzing the effect of NAD+, we analyzed the transcriptome of 4-month-old untreated Kdm8 mutant vs control hearts in which the myocardium is deteriorating toward heart failure." (PMID 38665902, 2023). "We hypothesized that deregulation of key transcription factors regulated by Kdm8 and controlling NAD+ metabolism underlies cardiac deterioration toward heart failure." (PMID 38665902, 2023). "Thus, Kdm8 is an H3K36me2 demethylase in cardiomyocytes that is required for cardiac homeostasis, and its deficiency causes progressive DCM and premature lethality due to heart failure." (PMID 38665902, 2023). "Therefore, counteracting H3K36me2 methylation of the promoter of metabolic regulators targeted by Kdm8 could be investigated as a strategy to maintain energy homeostasis and prevent the initiation of cardiac deterioration toward heart failure." (PMID 38665902, 2023). "Furthermore, higher expression of TBX15 defines a group of DCM-affected hearts with the strongest repression of metabolic gene networks, linking KDM8 and TBX15 with heart failure." (PMID 38665902, 2023). "Thus, Kdm8 regulates a transcriptional network controlling cardiac NAM metabolism, which is altered at the initiation of DCM before ATP and cardiac function decline toward heart failure." (PMID 38665902, 2023).
lentivirus infection (1 paper, 2019). Virus diseases caused by the Lentivirus genus. "Accordingly, KDM8 was overexpressed in LNCaP cells via lentivirus infection and cultured in androgen-deprived conditions." (PMID 30072740, 2019).
melanoma (1 paper, 2021). A malignant, usually aggressive tumor composed of atypical, neoplastic melanocytes.
ovarian carcinoma (1 paper, 2022). A malignant neoplasm originating from the surface ovarian epithelium. "We also verified that the transcription levels of the histone methylation-related genes EZH2, KDM8, STED5, and SMYD3 decreased significantly after MLN4924 treatment of ovarian cancer cells." (PMID 35864225, 2022).
cancer (28 papers, 2014 to 2026). A tumor composed of atypical neoplastic, often pleomorphic cells that invade other tissues. "The upregulation of KDM8 in these cancers has been linked with enhanced cell proliferation, migration, and invasion, which indicates its involvement in tumor progression." (PMID 37893043, 2023). "Together, these results suggest that the allostery-insensitive PKM2 variants confer increased regulation by KDM8 and promote aggressive cancer progression." (PMID 30911680, 2019). "Strikingly, Kdm8pos cancer cells were unevenly scattered along the latent time trajectory, with most residing near the root and decreasing in density towards late and terminal stages, suggesting that Kdm8 loss drove cancer cells into advanced transcriptomic states." (PMID 40909661, 2025). "Comparable to the findings in NSG mice, Kdm8-deficient 606T orthotopic tumors seeded 25-fold more pulmonary micrometastases compared to the control group, with many metastatic lesions appearing as individual cancer cells." (PMID 40909661, 2025). "Additive effects conferred by mutations in this cell-adhesion protein supports the hypothesis that KDM8 is likely a tumor suppressor and down-regulation of this gene may lead to a loss of epithelial phenotype and cell adhesion to promote cancer invasion." (PMID 31036064, 2019). "Interestingly, KDM8 has been linked to hypoxia-driven epigenetic regulation in cancer progression." (PMID 35512017, 2022). "On the other hand, dimethyl esters of 5-aminoalkyl-substituted derivatives of 2,4-pyridine dicarboxylic acid (compounds 19i and 19j) inhibited the catalytic activity of KDM8, and reduced the viability of several cancer cell lines." (PMID 40940894, 2025). "In the PTC mice, Kdm8 knockout in PDA cancer cells diminished the Myc gene signature, which was enriched near the root of the latent time trajectory." (PMID 40909661, 2025). "KDM8 was demonstrated to interact with pyruvate kinase muscle isozyme (PKM2) in cancer cells, impairing the tetramerization of PKM2 and blocking pyruvate kinase activity." (PMID 37185761, 2023). "Overexpression of KDM8 was observed in a variety of tumor tissues and knockdown of KDM8 compromised the growth of cancer cells (and this study)." (PMID 30072740, 2019). "Interestingly, another study reported that the expression of KDM8 was associated with cancer progression in OSCC patients, and the downregulation of KDM8 was important for the anti-cancer effects of silibinin in a model of patient-derived xenograft tumors." (PMID 40940894, 2025). "We have previously demonstrated that the knockdown of KDM8 compromised the growth of cancer cells." (PMID 30911680, 2019). "This implied that KDM8 is required for tight control of the cell cycle machinery and its reduction may lead to aberrant proliferation commonly seen in cancer cells." (PMID 31036064, 2019). "In addition, data from The Human Protein Atlas revealed that most malignant tumors also exhibited KDM8-positive IHC signals." (PMID 30911680, 2019). "Finally, a knockdown of the human KDM8 transcript inhibits cancer cell proliferation, and this effect is also dependent on the demethylase activity of KDM8." (PMID 24999627, 2014). "These contradictory observations may point to different roles of KDM8 in various cancers." (PMID 40940894, 2025). "Moreover, KDM8 has been revealed to positively regulate CCNA1 in cancer cell proliferation." (PMID 37893043, 2023). "Knockdown of KDM8 inhibited the transcription of target genes of PKM2-HIF-1α involved in glucose metabolism, which reduced the glucose uptake and lactate secretion in cancer cells." (PMID 37185761, 2023). "JMJD-5 shares homology with the mammalian JMJD5/KDM8, a JmjC-containing protein essential for mouse embryonic development, cancer growth and mitotic division." (PMID 28207814, 2017). "Considering these discoveries, both KDM8 and CCNA1 are potential targets for cancer treatment." (PMID 37893043, 2023).
cancer (continued). "This suggests that Kdm8 is required to maintain fully differentiated morphology in PDA, prompting us to test the hypothesis that the Kdm8-negative, less differentiated cancer cells might have transitioned into a mesenchymal state through EMT." (PMID 40909661, 2025). "Evaluation of anti-KDM8 immunostaining of prostate specimens from 121 cases revealed that 61% of malignant tumors showed high levels of KDM8 expression while the majority of normal or non-malignant prostate tissues displayed no detectable or low levels of KDM8." (PMID 30072740, 2019).